SIRPA (signal regulatory protein alpha)
Diseases named in the same sentence as SIRPA in open-access papers (continued):
Sharing a sentence is not in itself a finding about the gene and the disease.
tumor (continued). "Consequently, developing antibodies that specifically block SIRPα has gained interest as a potentially safer and more targeted approach to unleash anti-tumor immune responses while minimizing off-target effects." (PMID 40136470, 2025). "Macrophages can be induced to phagocytose tumor cells through SIRPα/CD47 blockade." (PMID 40725081, 2025). "In addition, we found that cryopreserved CUSA tissue fragments exhibited higher SIRPα expression on resident microglia compared to cryopreserved tumor biopsy." (PMID 40980437, 2025). "For example, there is evidence that the suppression of CD47/SIRPα signaling pathway components leads to the activation of tumor cell phagocytosis by macrophages, and high CD47 expression correlates with low PFS (progression-free survival) and OS (overall survival) rates." (PMID 39941714, 2025). "However, the molecular mechanisms by which tumor-intrinsic SIRPα modulates T-cell activity remain poorly characterized." (PMID 40589735, 2025). "Cluster of differentiation 47 (CD47), an immune checkpoint commonly referred to as the “don’t eat me” signal, plays a pivotal role in tumor immune evasion by inhibiting phagocytosis through interaction with signal regulatory protein alpha (SIRPα) on macrophages and dendritic cells (DCs)." (PMID 41179296, 2025). "Rao constructed hybrid vesicles based on tumor cell membrane vesicles, M1 macrophage-derived vesicles and platelet derived vesicles, and modified SIRPα protein on the hybrid vesicles through genetic engineering to block the immune escape pathway of tumor cells." (PMID 40717972, 2025). "The CD47 protein, frequently overexpressed on malignant cell surfaces, engages with signal regulatory protein alpha (SIRPα) expressed by myeloid cells (particularly macrophages) to transmit an immunosuppressive “don't eat me” signal, enabling tumor immune evasion through phagocytosis inhibition." (PMID 40892295, 2025). "Additionally, immune checkpoint pathways such as CD47/SIRPα inhibit phagocytosis by delivering a “don’t eat me” signal from tumor cells to macrophages." (PMID 41462587, 2025). "Similarly, in the orthotopic tumor model, we found that anti-SIRPα therapy inhibited the tumor growth and prolonged the survival of mice." (PMID 40523887, 2025). "Moreover, in the PDX model, we observed that SIRPα blockade therapy effectively inhibited tumor growth using HCC tissues from patients." (PMID 40523887, 2025). "Additionally, compared with the control group, SIRPα blockade therapy significantly inhibited the PD-L1 expression and polarization of myeloid cells to a pro-tumor status." (PMID 40523887, 2025). "In SIRPα−/− mice, significant tumor reduction is evident following RT, even in large tumors." (PMID 41296731, 2025). "However, following anti-IL-1β treatment, SIRPa arose as the receptor on macrophages for VEGFs in the KPC-4545 tumor." (PMID 39948655, 2025). "Therefore, to maximize the enhancement of macrophage phagocytosis, CD47/SIRPα blockade antibodies can be combined with tumor-opsonizing therapeutic antibodies that mount pro-phagocytic signaling through Fc/Fcγ interactions." (PMID 40136470, 2025). "Next, we hypothesized that the SIRPα-αMSLN4D8 LicMAb specifically binds to tumor cells in the presence of RBCs or lymphocytes." (PMID 40402266, 2025). "Despite the increased affinity of NOD SIRPα to huCD47 compared to the human -human interaction, maplirpacept can still reduce tumor burden, suggesting that it successfully blocks the interaction between NOD muSIRPα and huCD47 and still triggers NOD macrophages to phagocytose human tumors." (PMID 40078999, 2025). "Blockade of SIRPα enhances antigen presentation in macrophages, promotes the release of pro-inflammatory cytokines, and recruits T-cells to remodel the immunosuppressive tumor microenvironment." (PMID 40589735, 2025).
tumor (continued). "Therefore, targeting SIRPα has the potential to reprogram the tumor immune microenvironment, promoting systemic anticancer responses and preventing solid cancer progression." (PMID 40589735, 2025). "In addition to adaptive immune checkpoint of PD‐1/PD‐L1, the innate immune checkpoint SIRPα/CD47 plays an important role in regulation of tumor immune escape." (PMID 39665172, 2025). "Thirdly, the presence of a distinct cluster of SIRPα+ macrophages suggests that at least some phagocytic cells would be prone to stimulation by tumour-expressed CD47, thereby making them incapable of engulfing abnormal cellular bodies and limiting their anti-tumour role." (PMID 40870972, 2025). "To determine whether our model is useful for only MC38 tumors in WT and SIRPα−/− mice, we apply the model to other tumor and mouse models with combined RT and SIRPα-CD47 checkpoint inhibitions." (PMID 41296731, 2025). "These insights underscore the multifaceted role of SIRPα in the tumor ecosystem." (PMID 40589735, 2025). "We rationalized that engineering NDV to express an anti-CD47 monoclonal antibody or a SIRPα-Fc immunoadhesin would enable localized delivery of CD47-blocking agents to the tumor microenvironment, thereby enhancing therapeutic specificity while minimizing on-target, off-tumor effects." (PMID 41322194, 2025). "We then calibrate for the last parameters for tumor growth in SIRPα−/− mice with RT." (PMID 41296731, 2025). "Our data showed that 740 Y-P reversed the tumor inhibitory function of anti-SIRPα antibody." (PMID 40523887, 2025). "Besides regulating T-cells by presenting tumor antigens, SIRPα can further influence the differentiation and function of T-cells by regulating their own maturation." (PMID 40589735, 2025). "Blocking CD47/SIRPα signaling has been shown to inhibit A375 tumor growth in mice." (PMID 40082557, 2025). "Moreover, monotherapy with anti-SIRPα can alter the composition of the immune cell population in the tumor microenvironment, as evidenced by a significant increase in the proportion of M1 macrophages and a decrease in M2 macrophages." (PMID 40589735, 2025). "To investigate whether anti-SIRPα treatment could synergize with anti-PD-L1 therapy, we established orthotopic and spontaneous tumor models." (PMID 40523887, 2025). "Hence, the SIRPα-αMSLN LicMAb combines a tumor-restricted blockade of the CD47–SIRPα axis with a specific antitumor response while preventing on-target off-tumor toxicities." (PMID 40402266, 2025). "Notably, in syngeneic models of CD47/SiRPα blockade, either by injected Abs or coengineered T cells, tumor control (e.g., of MC38) can also be supported by “renewable” infiltration of endogenous T cells." (PMID 38828721, 2024). "Interestingly, the SIRPa protein has also been detected in normal astrocytes and lower grade glioma; however, its expression decreases with increasing tumor grade." (PMID 39194679, 2024). "Blocking the CD47/SIRPα pathway has been shown to activate macrophages and inhibit tumor growth." (PMID 38462636, 2024). "In this study, we detected a subset of SPP1 + macrophages expressing SIRPα, characterized by high lysosome and phagosome activity, T cell suppression ability, and enhanced antigen presentation ability, which is similar to macrophages engulfed tumor cells." (PMID 39696410, 2024). "In contrast, the high-affinity binding mediated by the anti-CEACAM5 arm induces the co-engagement of CD47 resulting in a “guided inhibition” of the CD47-SIRPα interaction between CD47 on CEACAM5-positive tumor cells and SIRPα on e.g., macrophages and natural killer cells." (PMID 38720892, 2024). "In favorable histology tumor tissues, we also observed SIRPA-positive macrophages." (PMID 38920727, 2024). "Consequently, rather than modulating accumulation of myeloid cells to impact tumor clearance, SIRPα blockade instead favors myeloid reprogramming to drive activation and tumoricidal function of other infiltrating populations, such as CD8 T cells and cDC1s." (PMID 38577107, 2024).
tumor (continued). "In a whole cancer cell vaccination model, vaccination with DXd-treated cancer cells led to activation of tumor-specific T cells when combined with an anti-mouse SIRPα (anti-mSIRPα) Ab, implying the benefit of combining DXd-ADCs with anti-SIRPα Ab on anti-tumor immunity." (PMID 38843278, 2024). "Overall, these studies suggest that combining HDACis with anti-CD47 could modulate the CD47/SIRPα axis, enhance phagocytosis, and decrease tumor growth by enhancing the antitumor immune response." (PMID 38414061, 2024). "Macrophages expressing SIRPA were rather dispersed throughout tumor tissues, but a higher density of smaller SIRPA-positive macrophages at necrotic areas was noticed, suggesting that these macrophages were newly recruited from the circulation in response to tumor-derived chemotactic factors." (PMID 38920727, 2024). "An alternative strategy is to target SIRPα, which has a much more restricted pattern of expression than CD47 and could potentially reduce the risk of on-target, off-tumor toxicities." (PMID 38319147, 2024). "Notably, PD-1 NVs, SIRPα NVs, and PD-1/SIRPα NVs significantly inhibited tumor growth by day 15, with hybrid nanovesicles exhibiting the most robust tumor suppression effect." (PMID 39588148, 2024). "Connection of CD47 and SIRPα could transmit inhibitory signals to prohibit macrophage phagocytosis, leading to immune evasion of tumor cells and ultimately promoting tumor development." (PMID 38317230, 2024). "The CD47/SIRPα axis has been known since 1998 and its role in neoplasms cannot go unnoticed." (PMID 38892394, 2024). "Furthermore, lactate produced by CRC cells inhibits the phagocytosis of TAMs by activating the Ap-2α/ETS-like-1 protein (Elk-1) axis, which increases levels of signal-regulatory protein alpha (SIRPα), dampening TAMs’ anti-tumor activity." (PMID 39119332, 2024). "Therefore, drugs targeting CD47 or SIRPα can block this signal, restoring the phagocytic function of macrophages, thereby achieving anti-tumor effects." (PMID 38370407, 2024). "This over-activation may lead to the cyclization of CD47 N-terminal pyroglutamate on the surface of tumor cells, and thus enhances the binding capacity to SIRPα." (PMID 38429732, 2024). "SIRPα functions to recognize overexpressed CD47 on the cell surface of tumor cells." (PMID 38256021, 2024). "However, anti-CD47 antibodies can competitively inhibit CD47’s binding to SIRPα and mediate macrophage phagocytosis, thereby targeting and killing tumor cells, such as those found in NSCLC." (PMID 38389925, 2024). "Therefore, engagement of SIRPA on macrophages by CD47 on tumor cells not only suppresses phagocytosis function of macrophages but also elicits the second signal, which would block M2 polarization and preserve M1 TAMs." (PMID 38920727, 2024). "However, we also observed a marked increase in SIRPα expression in CAR-M cells following coincubation with tumor cells." (PMID 39379603, 2024). "In addition, CD47 molecules on the surface of gETL NPs bound to the signal regulatory protein alpha receptor (SIRPα) on macrophages, preventing tumor cells from escaping the immune system, thus enhancing macrophage phagocytosis of tumor cells." (PMID 39802949, 2024). "Overall, these results provide compelling evidence that targeting SIRPα in CAR-modified macrophages not only augments their antitumor efficacy but also fosters a more robust immune response through T-cell recruitment in the tumor microenvironment." (PMID 39379603, 2024). "Here, SMC18 could effectively block PD-1/PD-L1 interaction and CD47/SIRPα interaction to achieve a synergic effect in inhibiting tumor growth." (PMID 38462636, 2024). "Furthermore, a study found that SIRPα is also a major regulator of tumor resistance to radiotherapy." (PMID 38167055, 2024).
tumor (continued). "CD47 monoclonal antibody (aCD47) can prevent the binding of CD47 and SIRPα, thereby promoting tumor cell phagocytosis by TAMs and DCs; however, many challenges remain to be overcome in application of aCD47 in osteosarcoma, including low immune response rates and systemic side effects." (PMID 38560565, 2024). "Remarkably, PD-1/SIRPα NVs maintained their tumor-binding preference even in the presence of RBCs." (PMID 39588148, 2024). "Therefore, inhibiting the interaction of CD47/SIRPα can be an effective strategy for enhancing the phagocytic clearance of tumor cells from the body." (PMID 38983860, 2024). "From our results, we hypothesized that the combination of NextA and targeting the CD47/SIRPα axis would decrease SM1 tumor growth." (PMID 38414061, 2024). "Delayed tumor growth was observed in mice treated with SIRPα-Fc twice a week." (PMID 39335665, 2024). "In both cases, KCs represented the majority of macrophages in normal liver, but a minor subset in tumoural liver, and expressed higher ID3, lower SIRPA and higher chemokine (CCL4, CCL3) and cytokines genes (IL18) in comparison to CD14+TIM4− tumour-associated macrophages." (PMID 38326607, 2024). "We then assessed if NextA could improve the antitumor effect of anti-SIRPα using the anti-SIRPα antibody clone P84, which has been shown to slow tumor growth of different tumor models." (PMID 38414061, 2024). "CD47, a ligand of SIRPA, predominantly expresses on tumor cells." (PMID 39220104, 2024). "Ever since the CD47-Signal-Regulatory Protein α (SIRPα) axis was identified as the initial checkpoint for tumor phagocytosis in the late 2000s, several other phagocytosis checkpoints responsible for enabling tumor cells to evade phagocytic elimination have come to light." (PMID 38881902, 2024). "SIRPα-VEGFR1 could achieve similar anti-tumor effects as a combination therapy and showed that co-targeting CD47 and angiogenesis did not intervene with their individual effects." (PMID 39335665, 2024). "In order to kill cancer cells and sabotage CD47-SIRPa (CD47-signal regulatory protein alpha) connections, the hybrid cell membrane nanovesicles, or hNVs, can interface with circulating tumour cells (CTCs) in vascular lumens and accumulate at the site of resection." (PMID 39720730, 2024). "However, the potential of CAR-modified macrophages with SIRPα blockade to improve antigen presentation, elicit a more durable memory T-cell response, and affect the tumor microenvironment warrants further investigation." (PMID 39379603, 2024). "In addition to targeting CD47, it has been found that SIRPα–blocking antibodies combined with CSF-1R inhibitors can stimulate the activation of anti-tumor macrophages." (PMID 39169402, 2024). "SIRPα inhibits macrophage phagocytosis; moreover, high expression of SIRPα may inhibit anti-tumor immune responses, leading to a poor prognosis in ESCC." (PMID 39678502, 2024). "The use of SIRPαFc (TTI-621), a decoy receptor that blocks the interaction of CD47 with SIRPα, was shown to provide a therapeutic benefit to patients with SS by significantly reducing the tumor load through the inhibition of the CD47-SIRPα signaling pathway in a clinical trial (NCT02663518)." (PMID 38915099, 2024). "PD-L1/PD-1- and CD47/SIRPα-targeting ΙO could eventually unleash the anti-tumor potential of activated lymphocytes and monocytes." (PMID 37232754, 2023). "In addition, we found that ST6GALNAC3 was positively correlated with the immune checkpoints (SIRPA, LILRB1, SIGLEC10) of tumor associated macrophages involved in tumor antigen recognition disorders." (PMID 37138287, 2023). "However, the combination effectively inhibited MC38 tumor growth compared to anti-SIRPα (P = 0.005) and HRT alone (P = 0.034)." (PMID 37291116, 2023).
tumor (continued). "Abnormally high expression of “do not eat me” signaling proteins, binding to macrophage surface related receptors, like SIRPα and Siglec10, can impair relevant signaling in macrophages, leading to reduced macrophage clearance and ineffective immune surveillance against tumor cells." (PMID 37484024, 2023). "The CD47/SIRPα axis requires SHP2 deneddylation to disrupt clearance of tumor cells." (PMID 36626230, 2023). "Furthermore, the SIRPα-/- can promote high levels of pro-inflammatory factors expression, induce tumor-specific cytotoxic CD8+ T cells expansion and activation, and exert efficient anti-tumor immunity in colorectal and pancreatic tumors." (PMID 36845095, 2023). "The disruption of the CD47/SIRPα axis reduces the ability of the tumor to escape phagocytosis." (PMID 36827121, 2023). "Previous studies have reported that in oncological diseases, the interplay between CD47 overexpression in tumour cells and counter ligand signal regulatory protein-α (SIRPα) expression in macrophages initiates the “don’t eat me” signal, which inhibits the capacity of macrophage phagocytosis." (PMID 38037074, 2023). "Inhibition of the CD47/SIRPα axis can reduce tumor size and metastasis in many tumor models." (PMID 36960057, 2023). "Then the three as‐obtained nanovesicles were mixed to form HMNVs, which could not only block the CD47/SIRPα signaling pathway but also promote M2‐to‐M1 reprogramming within tumor tissues, eventually leading to a remarkable effect of tumor immunotherapy." (PMID 37749882, 2023). "Though blockade of CD47/SIRPα signaling promoted macrophages phagocytosing tumor-originated mitochondrial DNA (mtDNA), it inhibited the phonological function of DCs which can reduce mtDNA degradation in DCs and activate DCs’ anti-tumor function by inducing type I interferon." (PMID 36845095, 2023). "Another explanation for the positive effect of SIRPα expression may be compensatory upregulation in a microenvironment where an active immune response threatens the tumor, similar to elevated SIRPα expression after HRT." (PMID 37291116, 2023). "TAMs also promote tumor immune evasion through expression of signal regulatory protein α (SIRPα)." (PMID 36911370, 2023). "We hypothesized that Kaiso is involved in immune evasion and thereby in tumor growth by modulating the THBS1/CD47/SIRPA axis." (PMID 37190208, 2023). "Notably, antitumor cytokines, such as IL‐1β, IFN‐γ, and IL‐12, were upregulated ≈15‐fold, whereas neutrophil‐related tumor immune checkpoints, such as SIRPα and PDL1, and protumor markers, such as VEGF and TGFβ‐R1, were downregulated significantly." (PMID 37565362, 2023). "Studies showed that recombinant protein TTI-621 which composed of the N-terminal domain of SIRPα fused to human IgG1 could suppress tumor growth by increasing macrophage-mediated phagocytosis of solid tumor cells." (PMID 36816959, 2023). "However, numerous studies indicate that administration of agents that block the CD47/SIRPα phagocytosis checkpoint leads to improved tumor clearance in vivo." (PMID 36787255, 2023). "Thus, mutant KRAS communicates with macrophages via the CD47/SIRPα axis and renders tumor cells insensitive to phagocytosis by macrophages." (PMID 36413402, 2023). "Blocking the SIRPα/CD47 axis could not only activate adaptive anti-tumor immune responses by promoting antigen cross-presentation by APCs, but also could activate innate immune responses by enhancing the cancer cell clearance by macrophages and DCs." (PMID 37510993, 2023). "Blocking CD47/SIRPα signaling enhances the anti-tumor effect of CAR-T cells." (PMID 38136311, 2023). "Since CD47 can competitively occupy SIRPα, the overexpression of CD47 on T-EVs may disrupt CD47/SIRPα signal and lead to enhanced macrophage-mediated phagocytosis of tumor cells." (PMID 37283792, 2023). "Recent research has shown that the CD47/SIRPα axis controls the destiny of tumor cells." (PMID 36726125, 2023).